BRCA1 (BRCA1 DNA repair associated)
Diseases named in the same sentence as BRCA1 in open-access papers (continued):
Sharing a sentence is not in itself a finding about the gene and the disease.
cancer (continued). "In a single-arm phase II clinical study, Olaparib had a 50% observed objective response rate and a 60% disease control rate in advanced cancer patients with germline BRCA1/2 mutation." (PMID 36717792, 2023). "It is of note that the only male with a homozygous BRCA1 mutation (P6) remains cancer-free despite reaching his late-teens – the oldest homozygous FA-S patient to do so." (PMID 38146508, 2023). "Olaparib, a poly (ADP-ribose) polymerase (PARP) inhibitor, has demonstrated effectiveness in treating ovarian, breast, and other cancers, particularly those with specific molecular subtypes including, but not limited to, BRCA1/2 mutations." (PMID 37553592, 2023). "The clinical use of PARPis as a synthetic lethal therapy in BRCA1- and 2-deficient cancers has already been proved to be an effective strategy." (PMID 37756561, 2023). "Forty-three patients (40.2%) had a family history of cancer, but germinal BRCA1/2 mutation was found in only 9 cases (56.3%) of the 16 in whom this analysis was performed." (PMID 38273853, 2023). "In conclusion, an increasing number of studies report the association of methylation in healthy tissue with cancer incidence of not only BRCA1 but also other genes with known roles in carcinogenesis." (PMID 37752189, 2023). "Germline DNA from 521 patients diagnosed with BC were retrospectively analyzed to assess PV and LPV frequency in cancer susceptibility genes other than BRCA1/2." (PMID 37628581, 2023). "Recurrent P/LP variants were identified in individuals diagnosed with cancer from distinct families, in the following cancer genes: BRCA1 (n = 3), LZTR1 (n = 3), HNF1A (n = 2), CHEK2 (n = 2), MITF (n = 2), and CHD4 (n = 2)." (PMID 37377903, 2023). "All these data note that there appears to be a linear relationship between RRM2 and BRCA1, which was further implicated the anti-cancer effects of COH29 via increasing DNA damage and decreasing the HR responses in ATRT." (PMID 38124207, 2023). "Primarily, PARPi has contributed to a synthetically lethal partnership in BRCA1/2-deficient cancers, although it has been shown to partner with many other proteins in a similarly lethal fashion." (PMID 37508568, 2023). "introduced the functional characteristics and structural insights of BRCA1 and the BRCA1 mutations on cancer progression." (PMID 37476378, 2023). "Supporting this observation, CST has been shown to promote polymerase inhibitor sensitivity in BRCA1-deficient cancer cells." (PMID 37760246, 2023). "DNA double-strand break misrepair is a potential driver of CIN and cancer predisposition as highlighted by mutations in BRCA1, ATM, NBS1 and BLM being causal in cancer syndromes associated with CIN." (PMID 36951111, 2023). "Although PARP1 inhibitors are primarily used in the clinic to treat cancers with an impaired homologous recombination signaling pathway (especially BRCA1 mutation), they have recently been used as part of an adjunctive therapy in other solid cancers." (PMID 37509303, 2023). "In the search for additional synthetic lethal targets, APE2 is over-expressed in many cancers and has emerged as a novel endonuclease that is required for the survival of cancer cells deficient in BRCA1, BRCA2 or TDP1." (PMID 37645072, 2023). "TRIP13 overexpression is common in BRCA1-deficient cancers, which leads to PARP-inhibitor resistance through conformational changes in REV7 and reduces drug sensitivity." (PMID 37529698, 2023). "Pathogenic variants in cancer predisposition genes such as BRCA1/2 are more common in early-onset BC compared to late-onset BC." (PMID 36980802, 2023). "The Δ11q isoform has also been shown to underlie a mechanism of resistance to PARP inhibitors and cisplatin in the management of BRCA1 mutated cancers." (PMID 38146508, 2023).
cancer (continued). "Mutations in the BRCA1 gene are mostly associated with hereditary cancers and are rarely found in sporadic cancers (compare more than 300 germline mutations for familial BC and/or OC, with only a few somatic ones in sporadic BC)." (PMID 36902416, 2023). "Of course, the probability of people suffering from cancer will also vary due to the different mutation locations in BRCA1 or BRCA2 genes." (PMID 36765522, 2023). "The mutation of BRCA1/2 genes has also been implicated in predicting therapeutic response in various cancer types." (PMID 37558683, 2023). "Cancers with BRCA1 and BRCA2 mutations are thought to be highly dependent on Polθ activity for their survival." (PMID 38001070, 2023). "The cancer associated BRCA1/2 mutations disrupt DNA double strand break (DSB) repair by homologous recombination (HR)." (PMID 37066268, 2023). "Other ways of regaining HRR proficiency without affecting theBRCA1-mutated status of the cell have been described,particularly in BRCA1-mutated cancer cells." (PMID 36872947, 2023). "Although less common, male carriers of BRCA1/2 mutations are also at higher risk of developing cancers compared to the unaffected population." (PMID 38203374, 2023). "Surveillance of cancer-free BRCA1/2 mutation carriers and expansion of insurance coverage for surgery are important future issues." (PMID 37957733, 2023). "PALB2 testing is important because of the associated high cancer risk, and including patients carrying P/LP variants in preventive and screening programs can improve their life expectancy similarly to BRCA1/2 carriers." (PMID 37686625, 2023). "For example, the use of disulfiram has been proposed for the treatment of cancers associated with BRCA1/2 mutations." (PMID 36345163, 2023). "This tactic has been validated in cancer patients with mutations in breast cancer gene 1 (BRCA1) and BRCA2 by the success of single agent poly (ADP-ribose) polymerase (PARP) inhibitor therapy." (PMID 38214010, 2023). "Here, we briefly discuss some of the ongoing clinical trials investigating combination approaches in BRCA1/2 deficient cancers." (PMID 37035242, 2023). "Summary of the Phase III clinical trials for the four BRCA1/2 mutated cancers (ovarian, breast, prostate, and pancreatic)." (PMID 37035242, 2023). "In the JAVELIN BRCA/ATM study, a pan-cancer approach was taken, with patients selected on the presence of pathogenic BRCA1/2 or ATM alterations." (PMID 37365284, 2023). "This reliance on the error-prone RAD52 in BRCA1/2-deficient cells can result in genomic rearrangements and instability, significantly contributing to an elevated mutation burden and advancing cancer progression." (PMID 38136334, 2023). "Since the identification of these genes in 1994 and 1995, evidence has grown to support the development of clear recommendations regarding the optimal management of BRCA1/2 PV carriers, through which cancer rates and all-cause mortality can be improved." (PMID 37887578, 2023). "After excluding ineligible patients, a total of 89 cancers in 81 patients with BRCA1-positive mutations and 83 cancers in 71 patients with BRCA2-positive mutations were included." (PMID 36905492, 2023). "Previous studies suggested that RAD52 is essential for the survival of BRCA1/2 deficient cancer cells, suggesting that a RAD52-dependent repair pathway is indispensable in BRCA1/2-deficient cells." (PMID 37777505, 2023). "Future investigations are needed to identify those factors that, in combination with the upregulation of ISG15, are required to alter fitness and drug sensitivity of BRCA1/2-mutated cancer cells." (PMID 37783689, 2023). "These hybrids, referred to as R-loops, also stimulate cGAS, and subsequently, IRF3, culminating in apoptosis, especially in BRCA1 (BReast CAncer susceptibility gene 1)-mutated cancer cells in vitro." (PMID 38139802, 2023).
cancer (continued). "PARP inhibitors (PARPis) have been applied to trigger synthetic lethality in BRCA1/2-mutated cancer cells by promoting the accumulation of toxic DSBs." (PMID 37066268, 2023). "Currently, the clinical management of women carrying BRCA1 PVs focuses on a combination of early diagnosis and cancer risk reduction through frequent screening, risk-reducing surgeries, and chemoprevention." (PMID 37296919, 2023). "Overall, our cell line data strongly support the notion that resistance to treatment and particularly to olaparib in BRCA1-deficient cancer cells is frequently associated with restoration of RAD51 foci formation, thus, signing for restored HR capacity." (PMID 37007122, 2023). "The protein encoded by the breast cancer susceptibility gene (BRCA1) contains at its C-terminal end two copies of a conserved 90–100 amino acids segment that was named BRCT (BRCA1 C-Terminus) domain." (PMID 37514027, 2023). "BRCA1/2 status was determined for all patients and relative risks (RRs) were calculated to evaluate cancer risk in relatives of the patients." (PMID 36861435, 2023). "Although PARP1i has been developed especially in BRCA1/2-deficient cancers, PARP1i resistance develops quickly in many patients." (PMID 36755963, 2023). "Strict cancer surveillance and risk-decreasing prophylactic surgeries have become a central component in the management of BRCA1/2 PV and LPV carriers." (PMID 37046793, 2023). "Overall, non-BRCA CSGs represented a greater proportion of PPGVs identified in BRCA-associated cancers than BRCA1/2 (6.9% versus 4.7%)." (PMID 37568048, 2023). "Altogether, these findings reveal that the IFNβ/ISG15 system controls fork stability in clinically relevant pathological contexts, increasing the fitness of BRCA1/2-deficient cancer cells and affecting the drug response." (PMID 37783689, 2023). "Those patients with a germline BRCA1/2 pathogenic/likely pathogenic variant are referred to clinical genetics to access familial cancer services." (PMID 38201604, 2023). "The approved drugs are used to treat cancers such as ovarian, breast, peritoneal, or prostate with BRCA1/2 mutations, which for breast and ovarian cancers account for 10–15% frequency." (PMID 37570820, 2023). "Although carrying a BRCA1/2 germline mutation significantly increases the risk of developing cancer, their prevalence in the general population is low (0.1–0.2%)." (PMID 38203374, 2023). "In humans, lung (log2-sens −1.68 vs −2.44), colon (log2-sens −0.98 vs −1.43), and ovarian (log2-sens −2.322 vs −2.325) cancer cell lines carrying BRCA1 mutation have higher sensibility to dasatinib compared to cell lines without BRCA1 mutation." (PMID 36658200, 2023). "This protein complex plays an important role in DNA damage repair and mutations in the BRCA1 gene predispose to increased risks of cancer." (PMID 36703164, 2023). "Poly (ADP-ribose) polymerase (PARP) inhibitors are effective against BRCA1/2-mutated cancers through synthetic lethality." (PMID 38069409, 2023). "As for patients diagnosed with TNBC or ER-low tumors, our findings indicate that BRCA1 promoter methylation should be explored as a potential risk factor for subsequent cancer development." (PMID 38053165, 2023). "Our analysis identified 2,793 human genes associated with various diseases, including those associated with cancers (such as BRCA1 and BRCA2) and cardiovascular diseases (such as PDE4D)." (PMID 36950105, 2023). "RANK aberrant activation has already been linked to basal-like cancers arising in BRCA1 mutation carriers, likely being an early event in preneoplasic BRCA1mut/+ breast tissue that favours oncogenesis." (PMID 36808257, 2023). "Cancer cells that are defective in homologous recombination repair such as those with BRCA1/2 mutations, are unable to accurately repair these PARPi-induced DNA DSBs and undergo cell death." (PMID 37582853, 2023).
cancer (continued). "PARP-deficient mice do not develop tumors and are otherwise healthy and fertile but the inhibition of PARP in BRCA1/2 deficient cancer cells has been shown to cause cell death." (PMID 35976445, 2023). "In hereditary BRCA1/2 mutation carriers, Castro found that the risk of stage T3/T4 cancer, nodal involvement, a Gleason score of 8 or higher, and metastases at the time of initial diagnosis was increased and that the survival time was also decreased." (PMID 37732318, 2023). "The positive detection rates for BRCA1/2, 6 high-penetrance genes, and 30 hereditary-cancer-associated genes were 2.1%, 2.5%, and 3.7%, respectively." (PMID 37174101, 2023). "These, in turn, cause DNA strand breaks that disrupt DNA repair mechanisms and contribute to the genomic instability that drives cancer development, as seen in BRCA1 and BRCA2 mutations." (PMID 38067328, 2023). "In this study, we investigate PLPV in BRCA1/2 and other cancer predisposition genes that are missed by testing only AJ founder BRCA1/2 mutations." (PMID 37535880, 2023). "For example, determining the appropriate classification of VUS can aid genetic counseling 46, because deleterious BRCA1 variants are likely to increase cancer risk." (PMID 36593954, 2023). "The HR-deficiency-specific pattern, “Signature 3” is seen with BRCA1/2 loss in several cancer streams, including breast, ovarian, prostate and gastric." (PMID 36831687, 2023). "For BRCA1/2, we also compared patient backgrounds and cancer types with somatic and germline variants in NOP and pathogenic variants in F1CDx, consistent with ESMO recommendations." (PMID 37916805, 2023). "BRCA1/2 is an important DNA damage repair protein involved in the HR pathway, and after DSBs, BRCA1/2-deficient cancer cells die because DSBs cannot be repaired by the HR pathway." (PMID 37381029, 2023). "Mutations in key DNA repair genes, such as breast cancer 1 (BRCA1) and/or breast cancer 2 (BRCA2), induce genomic instability and promote tumorigenesis." (PMID 36902170, 2023). "Initially, they were developed as dissipaters of DNA repair and potent sensitizers of cancer cells to chemotherapy, but they also showed a significant independent effect on patients with mutations in the HR genes, primarily BRCA1." (PMID 36902416, 2023). "It has a profound influence on fundamental studies, diagnoses, and treatment approaches of BRCA1-associated cancers." (PMID 36902416, 2023). "Most cases of HBOC are caused by mutations in the breast cancer 1 (BRCA1) or breast cancer 2 (BRCA2) genes." (PMID 34989978, 2023). "BRCA1 or BRCA2 (BRCA1/2)-mutated cancer cells are effectively targeted by poly ADP ribose polymerase (PARP) inhibitors, leveraging the principle of synthetic lethality." (PMID 38139386, 2023). "Women with BRCA1 mutations are more likely to develop malignant pathology at a younger age, so one would expect an increase in occult cancers at the time of RRSO compared with BRCA2 carriers." (PMID 36837501, 2023). "Although homologous recombination deficiencies (HRDs) were initially described in cancers with germline mutations of BRCA1/2, the genetic and epigenetic inactivation of other homologous recombination components can also lead to HRDs." (PMID 38201253, 2023). "Among these features, genomic markers are closely related to mutations and cancer metastasis, with BRCA1, BRCA2, and PIK3CA being previous impact markers." (PMID 36765522, 2023). "We hope that the knowledge gathered here highlights both the necessity of BRCA1 research and the potential for novel strategies to prevent and treat cancer in individuals carrying BRCA1 mutations." (PMID 37762577, 2023).
cancer (continued). "Prevention or early detection of BRCA1/2-related cancers is predicated on the identification of BRCA1/2 mutation carriers." (PMID 37291133, 2023). "For unaffected women, earliest age of family cancer diagnosis was significantly associated with PV status only for BRCA1 (OR 2.34, 95% CI 2.13–2.56) and BRCA2 (OR 1.25, 95% CI 1.16–1.35)." (PMID 37084156, 2023). "Several PARP inhibitors gained FDA approval for treating cancers that harbor mutated BRCA1 or BRCA2 genes." (PMID 37510250, 2023). "Another factor related to the decrease in the antioxidant capacity of cancer cells is a defect in the expression of the BRCA1 gene, which reduces the expression of BRCA1, causing the negative regulation of Nrf2." (PMID 37841775, 2023). "For individuals of non-AJ ancestry, limiting evaluation to only the three AJ founder BRCA1/2 mutations missed the majority of all mutations in actionable cancer risk genes." (PMID 37535880, 2023). "In our data, the PV c.4035del did not provide statistically significant evidence for elevated BC risk compared with OC risk, supporting the observation that this BRCA1 PV is associated with relatively equivalent risks of both cancers." (PMID 37296919, 2023). "Studies show that BRCA1 or BRCA2 dysfunction profoundly sensitize cells to poly-ADP ribose polymerase (PARP) inhibitors (PARPi) due to HR repair defects in BRCA1 or BRCA2-deficient cancer cells." (PMID 36794849, 2023). "In adult patients with cancer, BRCA1 and BRCA2 variants are tissue-restricted biomarkers for PARP inhibitor sensitivity." (PMID 36585449, 2023). "The genetic principle of synthetic lethality is clinically validated in cancers with loss of specific DNA damage response (DDR) pathway genes (i.e. BRCA1/2 tumor suppressor mutations)." (PMID 37398210, 2023). "Our study found an overall 4.1% rate of cancer in mutation carriers undergoing risk-reducing surgery, including two with BRCA1 mutation and one with BRCA2 mutation." (PMID 37386498, 2023). "As a result, international guidelines recommend that all BRCA1\2 mutation carriers be offered risk-reducing bilateral salpingo-oophorectomy at an early age to reduce the risk of cancer and decrease the mortality rate of this high-risk population." (PMID 36614207, 2023). "Cancer cells harboring mutations in genes involved in homologous recombination (HR)‐mediated DNA repair such as BRCA1 and BRCA2 are exquisitely sensitive to poly(ADP‐ribose) polymerase (PARP) inhibitors." (PMID 37492888, 2023). "This has allowed investigators to describe the phenotype of BRCA1/2 in terms of penetrance, age at diagnosis, strength of family history, histologic subtypes, and association with other cancers." (PMID 37084156, 2023). "R-loop formation in BRCA1/2 deficient cells causes genomic instability, which increases mutation rates and, ultimately, cancer risk." (PMID 37108225, 2023). "Loss-of-function mutations in BRCA1 not only increase the risk of cancer development in humans and dogs but also increase the genomic stability of cells." (PMID 36658200, 2023). "The homologous recombination (HR) repair pathway defect, caused by the germline pathogenic mutations of the breast cancer type 1 susceptibility gene (BRCA1), is associated with CRC." (PMID 38067284, 2023). "Recent research has identified potential therapeutic targets for cancers associated with BRCA1 mutations." (PMID 37762577, 2023). "BRCA1 mutation-containing cancers demonstrate varying responses to PARP inhibitor (PARPi) therapy, in part due to differences in the severity of HR malfunction." (PMID 38001070, 2023). "Overall, 15 patients out of 521 (2.9%) showed PVs and LPVs in five cancer-predisposing genes other than BRCA1/2 (PALB2, CHEK2, ATM, RAD51C, and RAD51D)." (PMID 37628581, 2023).